LGALS3 (galectin 3)
Diseases named in the same sentence as LGALS3 in open-access papers (continued):
Sharing a sentence is not in itself a finding about the gene and the disease.
Hyperglycemia (26 papers, 2007 to 2026). An increased concentration of glucose in the blood. "On the other hand, although underlying HTN and hyperglycemia were associated with galectin-3, the association was attenuated after adjustment of certain variables." (PMID 37240626, 2023). "Galectin-3–deficient (Galectin-3−/−) mice exhibit remarkable resistance to streptozotocin (STZ)–induced hyperglycemia development, accompanied by notable down-regulation of interferon-γ (IFN-γ), tumor necrosis factor–α, interleukin-17 (IL-17), and inducible nitric oxide synthase in macrophages." (PMID 41477833, 2026). "Several studies suggested that hyperglycemia was linked to galectin-3." (PMID 37626284, 2023). "Regarding hyperglycaemia, high levels of galectin-3 were associated with lower levels of HbA1c46." (PMID 34561496, 2021). "Available data showed that hyperglycemia was associated with galectin-3 upregulation." (PMID 31080833, 2019). "Transgenic overexpression of Galectin-3 in pancreatic β cells has been shown to attenuate hyperglycemia in STZ-induced diabetic mice, suggesting its antiapoptotic role within pancreatic β cells." (PMID 41477833, 2026). "Patients with elevated HbA1c (≥6.45) and hyperglycemia (glucose ≥ 120 mg/dL) demonstrated the highest median values of galectin-3 (115.27 ng/mL [IQR: 109.23–132.13]) and sICAM-1 (57.53 ng/mL [IQR: 54.76–62.79])." (PMID 40733621, 2025). "Subgroup analyses in our study supported these observations by demonstrating that both galectin-3 and sICAM-1 levels were highest in patients with poor glycemic control (HbA1c ≥ 6.45) and hyperglycemia (glucose ≥ 120 mg/dL)." (PMID 40733621, 2025). "In summary, galectin-3 affects EV71 replication in our cellular model and its variant, rs4644, is associated with hyperglycemia in the clinical setting." (PMID 28002441, 2016). "Elevated galectin-3 levels might be a vital protective mechanism among those exposed to hyperglycemia during pregnancy." (PMID 37626284, 2023). "Future studies were required to validate whether plasma galectin-3 might become a potential biomarker for hyperglycemia during pregnancy." (PMID 37626284, 2023). "Second, it supports the clinical association between galectin-3 SNP rs4644 and EV71-induced hyperglycemia, suggesting altered glucose metabolism might underlie clinical severity via mechanisms that involve galectin-3." (PMID 28002441, 2016). "Down-regulation of GLUT4 mRNA and protein in the endothelium and muscle of galectin-3 (−/−) mice may explain the hyperglycemia experienced by these mice, and suggests a role for galectin-3 in the regulation of glucose uptake." (PMID 26047815, 2015). "Since galectin-3 was demonstrated to be involved in inflammatory and fibrotic processes as well as cardiac remodeling, we hypothesized that galectin-3 might be a specific and complementary biomarker particularly for hyperglycaemia induced cardiac impairment." (PMID 34561496, 2021). "In addition, the A allele of rs4644, which mimics the findings in galectin-3 ablated cells, was associated with lower EV71 titers in our cellular model, and clinically the AA genotype was protective against higher levels of hyperglycemia, an indicator for severe EV71 infection." (PMID 28002441, 2016). "Galectin-3 (−/−) mice display greater metabolic derangement in response to HFD compared to WT mice, including both extreme hyperglycemia and impaired response to glucose challenge." (PMID 26047815, 2015).
ischemia (26 papers, 2010 to 2025). A hypoperfusion of the BLOOD through an organ or tissue caused by a PATHOLOGIC CONSTRICTION or obstruction of its BLOOD VESSELS, or an absence of BLOOD CIRCULATION. "Next, IL-23R-Y416FΔICD signaling deficient mice and IL-23R mice were sacrificed after ischemia and 24 h of reperfusion and the hearts were stained for αSMA, HA and Galectin-3." (PMID 30459442, 2018). "Similarly, Galectin-3 (LGALS3) participates in the modulation of the inflammatory response as an important mediator of the reparative process driven by macrophages, and it has been associated with ischemia injury progression as well." (PMID 39004727, 2024). "The main finding is that 10 genes (Clec5a, CD14, Fgr, Hck, Anxa1, Lgals3, Irf1, Lbp, Ptx3, Serping1) may represent key molecular links underlying acute activation of immune cells in the hippocampus in response to experimental ischemia." (PMID 34944656, 2021). "Previous studies reported that LGALS3 + microglia were abundant in the core region after ischemia, which supports our results." (PMID 38082331, 2023). "The discriminatory ability of renalase for ischemia prediction was statistically higher compared to those of galectin-3 (DeLong test: p = 0.014) and GDF-15 (DeLong test: p = 0.046) and similar to that of sST2." (PMID 34395559, 2021). "In a research to investigate the effects of galectin-3 on MI/RI, C57B6/J wild-type (WT) mice and galectin-3 knockout (KO) mice were used to establish murine model with MI/RI for 30 min of ischemia and 24 h of reperfusion." (PMID 34055195, 2021). "Expression of another gene, Lgals3, was related to microglial activation in experimental ischemia in gerbils." (PMID 34944656, 2021). "Within the central and peripheral nervous system, galectin-3/Mac-2 is expressed by microglia, macrophages and Schwann cells that phagocytose myelin following induction of experimental allergic encephalomyelitis, ischemia, and sciatic nerve transection." (PMID 20507613, 2010). "Indeed, galectin-3 was markedly up-regulated in the myocardium and cardiomyocyte in response to ischemia/reperfusion and hypoxia/reoxygenation, respectively." (PMID 34588985, 2021). "These galectin-3 expressing cells in the nervous system, including microglia, macrophages, and Schwann cells, are known to be involved in myelin phagocytosis in experimental allergic encephalomyelitis, ischemia, and axonal injury." (PMID 21187959, 2010). "In patients with LVEF <45% (HFrEF), independent predictors of ischemia were BNP (p = 0.001), renalase (p < 0.001), sST2 (p = 0.004), galectin-3 (p = 0.003), GDF-15 (p = 0.001), and syndecan-1 (p < 0.001)." (PMID 34395559, 2021). "The AUCs of renalase (0.753), galectin-3 (0.726), and GDF-15 (0.735) were similar and were non-inferior compared to BNP, regarding ischemia prediction." (PMID 34395559, 2021).
non-small cell lung carcinoma (23 papers, 2010 to 2025). A group of at least three distinct histological types of lung cancer, including non-small cell squamous cell carcinoma, adenocarcinoma, and large cell carcinoma. "As for galectin-3, previous studies had showed the inconsistent association of galectin-3 in the clinical outcomes of non-small cell lung cancer." (PMID 35280768, 2022). "Galectin-3 associated with cyclin D1 expression was also studied in non-small cell lung cancer." (PMID 30410421, 2018). "Liang and co-workers showed in non small cell lung cancer, that not only galectin-3 expression in tumor tissue could be connected with occurrence of metastasis, but also higher serum level of galectin-3 could indicate on increased risk of occult metastasis." (PMID 22024187, 2011). "Dong and colleagues reported that cilengitide reversed erlotinib resistance by inhibiting the Galectin-3/KRAS/RALB/TBK1/NF-κB signaling pathway in non-small cell lung cancer." (PMID 35142593, 2022). "In non-small cell lung carcinoma, high galectin-3 expression correlated with a poor response to PD-1 blockade in a small cohort of patients." (PMID 34572756, 2021). "This study was to explore the serum levels of Galectin-3 and its clinical significance in non-small cell lung cancer (NSCLC) patients." (PMID 32429635, 2020). "We didn't reveal any important correlations between clinicopathological findings and galectin-3 and cyclin D1 expression and in non small cell lung cancer." (PMID 22024187, 2011). "The aim of this study was the evaluation of correlations between clinicopathological findings and cyclin D1 and galectin-3 expression in non-small cell lung cancer (NSCLC)." (PMID 22024187, 2011). "The aim of this study was the evaluation of correlations between clinicopathological findings and cyclin D1 and galectin-3 expression in non-small cell lung cancer." (PMID 22024187, 2011). "Immunohistochemical expression of galectin-3 was evaluated in a consecutive series of 81 radically resected non-small cell lung carcinomas (NSCLCs)." (PMID 23658855, 2010). "A population of the non-small-cell lung cancers examined was found to over-express the galectin-3 gene at levels three times higher than those of normal epithelial cells." (PMID 23658855, 2010). "In accordance with what we observed, the expression of Galectin-3 was identified as a marker for a low overall survival of different cancers such as colorectal, ovarian, and non-small cell lung cancer, serving as an anti-apoptotic, proangiogenic and invasive agent." (PMID 34503258, 2021). "In addition, another study in non-small cell lung cancer observed higher expression of cyclin D1 in galectin-3 free tumor tissues." (PMID 31832021, 2019). "In squamous cell carcinoma (SCC) galectin-3 expression was positive in 11 from 24 tumor specimens (45.83%), in adenocarcinoma in 4 from 15 (26,67%), in large cell carcinoma in 2 from 4 (50%) and in non- small cell lung cancer of unspecified type in 1 from 4 (25%)." (PMID 22024187, 2011). "However, higher cyclin D1 expression was found in galectin-3 negative tumor tissues and the differences in correlations between their expressions in two main histopathological types of non-small cell lung cancer were also discovered." (PMID 30410421, 2018). "The authors concluded that galectin-3 may be a phenotypic marker that excludes small-cell lung cancer and may represent a novel target molecule in non-small-cell lung cancer therapy." (PMID 23658855, 2010).
thyroid tumor (23 papers, 2005 to 2026). A benign or malignant neoplasm affecting the thyroid gland. "Incorporating galectin-3 into routine histopathological evaluation can improve diagnostic accuracy, especially in indeterminate or follicular-patterned thyroid neoplasms." (PMID 41737063, 2026). "Galectin-3 is a notable protein marker for thyroid tumors, and we confirmed the induction of galectin-3 in an antibody array and western blot analysis." (PMID 34208730, 2021). "The up-regulation of galectin-3 was showed during tumorigenesis in human neoplasms of the thyroid, colon, liver, and brain." (PMID 34322092, 2021). "We propose to study HBME-1 and galectin-3 expression and BRAF V600E mutation in thyroid neoplasms and do a comparative analysis to determine whether there is a correlation between BRAF V600E expression and that of HBME-1 and galectin-3." (PMID 34934597, 2021). "In the thyroid, expression of this protein has been described in differentiated follicular cancer, suggesting that the immunohistochemical study of galectin-3 may be a potential marker of malignancy in thyroid neoplasms." (PMID 22188859, 2011). "For example, a study of 100 benign and 105 malignant thyroid tumors using a panel of 57 molecular markers found an association of tumor pathology with the expression of a subset of markers including cytokeratin 19 (CK19), LGALS3, HBME-1, VEGF, AR, p16, and AURKA." (PMID 25887408, 2015). "Messenger RNA expression for individual marker genes was demonstrated in 109 (TFF3), 99 (LGALS3), 95 (ADM3), 84 (HGD1) and 67 (PLAB) of 111 fine-needle biopsies obtained from the thyroid tumours and in all 45 samples obtained from normal thyroid tissues." (PMID 22223087, 2012). "In addition, three novel gene combinations were found to be significantly altered in benign vs malignant thyroid tumours (ADM3/TG, HGD1/TG and LGALS3/TG)." (PMID 22223087, 2012). "In addition to these molecular markers, Galectin-3, Hector Batiffora mesothelial antigen-1 (HBME-1), and cytokeratin-19 have been immunohistochemically analyzed in thyroid tumors." (PMID 23049733, 2012). "On a single gene basis, FNAB of histologically proven malignant thyroid tumours (n=18) showed significantly lower mRNA expression levels for TFF3 and HGD1 and significantly higher mRNA levels for ADM3 and LGALS3 compared with FNAB of benign thyroid tumours (n=93)." (PMID 22223087, 2012). "One method that may be used to evaluate diagnostically difficult specimens is IHC, as the triad of galectin-3, Hector Battifora mesothelial cell 1 (HBME-1), and cytokeratin 19 (CK19) is well established as a means of differentiating between various thyroid neoplasms." (PMID 26550511, 2015). "In summary, immunoexpression of galectin-3, CK19 and HBME-1 is an important supplementary test in the diagnosis of thyroid neoplasms, albeit it does not replace the conventional histomorphological examination." (PMID 20181018, 2010).
aortic stenosis (22 papers, 2011 to 2024). Aortic valve stenosis is a aortic valve disease caused by the incomplete opening of the aortic valve. "Our results show that high levels of baseline biomarkers BNP, NT-proBNP, Troponin and Galectin-3 all predicted increased all-cause mortality in a wide population of patients with aortic stenosis." (PMID 34067808, 2021). "Serum level of galectin-3 was measured and 2-dimensional echocardiography was performed to characterize the extent of cardiac damage using a recently published aortic stenosis staging classification." (PMID 33690718, 2021). "In aortic valves from patients with aortic stenosis, galectin-3 co-localized with the α-smooth muscle cell markers actin and vimentin." (PMID 28471381, 2017). "Galectin-3 was found to be significantly up-regulated in hypertrophied hearts of patients with aortic stenosis." (PMID 21189092, 2011). "Studies on the correlation between galectin-3 and fibrosis in patients with various heart diseases, such as chronic Chagas disease cardiomyopathy and aortic stenosis (AS), have been reported in humans." (PMID 34722704, 2021).
bladder cancer (22 papers, 2010 to 2025). "Among these, galectin-3 has emerged as a promising diagnostic and prognostic marker in bladder cancer." (PMID 40252176, 2025). "Using the TCGA database of cancers, the TSC2 loss-of-function expression signature, as well as levels of LGALS3, were associated with bladder cancers harboring TSC1/TSC2 inactivating mutations." (PMID 28695825, 2017). "Moreover, patients with muscle-invasive tumours also have higher serum levels of galectin-3 than those with Ta tumours, conferring to this glycoprotein a diagnostic and stratification value for bladder cancer patients." (PMID 29207682, 2017). "Bladder cancers with mutations in TSC1 or TSC2 also had higher levels of galectin-3, suggesting that other diseases linked with mutations in these genes may also result in increased production of galectin-3." (PMID 28695825, 2017). "The serum level of galectin-3 could assist as a diagnostic marker in bladder cancer patients." (PMID 31832021, 2019). "In bladder cancer, galectin-3 functions as an anti-apoptotic molecule, promoting tumor cell survival." (PMID 40252176, 2025). "Serum levels of galectin-3 were found to be significantly elevated in bladder cancer patients compared to controls, with strong correlations to tumor type, stage and grade." (PMID 40252176, 2025). "Previous studies showed that the main target of MCP is galectin-3, whose overexpression has been reported in multiple cancer types, including breast, lung, gastric, liver, and bladder cancers." (PMID 35334790, 2022). "In fact, bladder cancer patient’s serum levels of galectin-3 are considerably higher than control groups, and are correlated with tumour type, stage and grade." (PMID 29207682, 2017). "For example, PSM and Galectin-3 were up-regulated in bladder cancer and those patients with high level expressions had a worse outcome." (PMID 27626805, 2016). "More recently, proteomic analysis on exosomes secreted by the bladder cancer cell line HT1376 showed these contain Galectin-3." (PMID 25869099, 2015). "For that reason the measurement of serum galectin-3 will be helpful in diagnosis of bladder cancer, if it is clinically suspected." (PMID 23658855, 2010). "Interestingly, in contrast to galectin-3 and galectin-1, galectin-8 appears to play an opposing role in bladder cancer progression." (PMID 40252176, 2025). "One study reported that Galectin-3 can bind to MICA, which is a ligand to the activating NK cell receptor NKG2D, and that this Galectin-3-MICA complex caused disturbed interaction with NKG2D and thereby reduced NK cell killing of bladder cancer cells." (PMID 39759523, 2024). "Therefore, galectin-3 may be the potential target of cancer therapy if we consider citrus extract as a preventive and therapeutic agent for bladder cancer." (PMID 35334790, 2022).
non-alcoholic steatohepatitis (22 papers, 2018 to 2026). "This idea is currently explored as pharmacological galectin-3 inhibitors are under evaluation in clinical trials for the treatment of non-alcoholic steatohepatitis." (PMID 38777863, 2024). "Galectin-3 has also been related to lipid content in the liver through interactions with the lipid uptake marker CD36 and PPAR-γ, and ablation of galectin-3 in mice provided a protective effect on non-alcoholic steatohepatitis by reducing liver steatosis." (PMID 38777863, 2024). "A role for LGALS3 in promoting fibrosis and inflammation in mouse models of nonalcoholic steatohepatitis has been also proposed." (PMID 35046474, 2022). "In contrast, other studies have reported that galectin-3 ablation protected the mice from the diet-induced non-alcoholic steatohepatitis." (PMID 34778306, 2021). "Indeed, the evidence regarding the role of galectin-3 in non-alcoholic fatty liver disease and non-alcoholic steatohepatitis is also controversial." (PMID 34778306, 2021).